CST7 (cystatin F)
Diseases named in the same sentence as CST7 in open-access papers (continued):
Sharing a sentence is not in itself a finding about the gene and the disease.
prion disease (3 papers, 2017 to 2024). A transmissible disease that is caused by a protein that is able to induce abnormal folding of normal cellular proteins, leading to characteristic spongiform brain changes, which are associated with neuronal loss without an inflammatory response. "Coinciding with the cathepsin family of genes in microglia, Cst7 is also implicated in the neuroinflammation that occurs with Alzheimer’s and prion disease." (PMID 38385967, 2024). "Compared to Serpina3n and to Gfap, a marker of astrogliosis typically associated to prion disease, Cst7 mRNA upregulation occurred earlier during prion disease." (PMID 28178353, 2017). "Early and robust upregulation of Cst7 mRNA levels and of its cognate protein was validated in additional mouse models of prion disease." (PMID 28178353, 2017). "To validate the upregulation of Cst7 transcripts during prion disease identified with the microarray, we performed quantitative RT-PCR analysis in brains of prion-infected versus control mice (the latter injected with NBH)." (PMID 28178353, 2017). "To gain a first insight into cystatin F levels in neurologic conditions other than prion diseases, we analyzed a first cohort of patients with several neurodegenerative and neuro-infectious/inflammatory conditions." (PMID 28178353, 2017). "The early and strong upregulation of Cst7 mRNA during prion disease, along with the fact that cystatin F can be secreted into the extra-cellular space, prompted us to investigate the role of cystatin F as a possible surrogate biomarker in prion diseases." (PMID 28178353, 2017). "Our results validate cystatin F as a useful biomarker of early pathogenesis in experimental models of prion disease, and point to unexpected species-specific differences in the transcriptional responses to prion infections." (PMID 28178353, 2017). "We next explored the role of cystatin F as a potential biomarker for prion diseases." (PMID 28178353, 2017). "In light of these data, we asked whether neurologic conditions with prominent neuroinflammation/microgliosis other than prion disease may result in the upregulation of Cst7 mRNA." (PMID 28178353, 2017). "We next aimed at studying cystatin F protein levels in mouse models of prion diseases." (PMID 28178353, 2017).
breast carcinoma (2 papers, 2019 to 2024). "This study has some limitations, Additional large-scale cohort studies are required to confirm the predictive and diagnostic capabilities of CST7 and miR-4793-5p in various subtypes and stages of breast cancer." (PMID 39552709, 2024). "On the other hand, Utilizing GSE57897 gene expression data analysis showed hsa-miR-4793-5p expression was increased in BC patients, hsa-miR-4793-5p is a type of microRNA that has been implicated in breast cancer, in sillico studies showed hsa-miR-4793-5p has a binding site on CST7 gene." (PMID 39552709, 2024). "CST7 is a protein-coding gene that has been associated with the progression of various cancers, including breast cancer, it has been suggested that CST7 may play a role in modulating the tumor microenvironment and influencing cancer cell behavior." (PMID 39552709, 2024). "Prior to further investigation, it is imperative to carry out functional investigations in order to clarify the precise mechanisms by which miR-4793-5p controls CST7 and the impact of this interaction on the advancement of breast cancer." (PMID 39552709, 2024). "An examination of CST7 and miR-4793-5p expression at the individual cell level in breast cancer has the potential to offer more detailed understanding of their functions in particular cell types within the tumor microenvironment." (PMID 39552709, 2024). "Targeting the interaction between hsa-miR-4793-5p and CST7 for therapeutic purposes in breast cancer holds great potential." (PMID 39552709, 2024). "For f uture studies, it would be valuable to investigate the therapeutic potential of targeting the miR-4793-5p/CST7 axis in the context of breast cancer." (PMID 39552709, 2024). "Modulating the expression or activity of hsa-miR-4793-5p and CST7 through targeted approaches may offer a novel avenue for developing tailored treatments for breast cancer." (PMID 39552709, 2024). "Creating a comparable scoring system for breast cancer, which might include the evaluation of CST7 and miR-4793-5p expression, has the potential to offer significant understanding regarding the effectiveness of immunotherapy and the prediction of prognosis." (PMID 39552709, 2024). "Analyzing their expression profiles in different cancer tissues and cell lines could elucidate whether the regulatory effects observed in breast cancer are context-specific or if miR-4793-5p and CST7 play similar roles in other malignancies." (PMID 39552709, 2024). "This discovery reinforces our emphasis on CST7 in breast cancer and indicates that its significance may apply to several types of cancer." (PMID 39552709, 2024). "Therefore, both CST7 and hsa-miR-4793-5p are being researched for their potential roles in breast cancer development and progression." (PMID 39552709, 2024). "Additionally, exploring the feasibility of using miR-4793-5p and CST7 as targets for novel therapeutic interventions, such as RNA-based therapeutics, could provide insight into potential treatment options for breast cancer." (PMID 39552709, 2024). "Understanding the broader impact of miR-4793-5p and CST7 across varied cancer types could provide valuable insights for developing targeted therapies with potential applications beyond breast cancer.context of breast cancer progression." (PMID 39552709, 2024). "Further research should examine the involvement of CST7 in the infiltration of immune cells in breast cancer tissues and analyze possible connections between CST7, IL1B, and ITGA5 in relation to breast cancer." (PMID 39552709, 2024). "Additionally, investigating the relationship between CST7 and miR-4793-5p expression and how they affect the response to different treatment methods, such as targeted treatments and immunotherapies, could improve our comprehension of their functions in managing breast cancer." (PMID 39552709, 2024).
demyelination (2 papers, 2012 to 2024). "Recent studies have demonstrated that cystatin F, a potent endogenous cysteine protease inhibitor, is selectively expressed in immune cells in association with inflammatory demyelination in central nervous system diseases." (PMID 23285090, 2012). "Cystatin F has recently been found to play a role in modulating disease severity in pre-clinical mouse models of demyelination, including experimental autoimmune encephalomyelitis (EAE), as well as toxin and genetic models of disease." (PMID 38879499, 2024).
glioblastoma (2 papers, 2023 to 2025). The most malignant astrocytic tumor (WHO grade IV). "In vitro co-cultures of cystatin F-expressing microglial cells and glioblastoma stem-like cells were used to assess NK cell function." (PMID 41229419, 2025). "Increased cystatin F levels are correlated with poor prognosis in glioblastoma and contribute to immunosuppression by reducing the cytotoxicity of immune cells." (PMID 41229419, 2025). "Cystatin F’s expression is elevated in several types of cancer, such as colorectal cancer, liver metastasis, pancreatic ductal adenocarcinoma, and glioblastoma (GBM), as shown in our previous study." (PMID 41229419, 2025). "We have confirmed co-expression of cystatin F with immune-related markers (CD45, LAG3, TIM3, PD1 and DNAM1) on a protein level in glioblastoma tissue sections." (PMID 41229419, 2025). "Publicly available data from TIMER database reveals a correlation of cystatin F gene (CST7) expression in glioblastoma with immune infiltration (negative correlation with tumor purity) (left)." (PMID 41229419, 2025). "Therefore, we analysed the glycosylation profile of internalized cystatin F. As a model, we used U-251 MG glioblastoma cells that do not express cystatin F. However, these cells stained positive for cystatin F after culturing in conditioned media from NK-92 or U-937 cells." (PMID 38092995, 2023).
heart attack (2 papers, 2021 to 2025). "CST7 is associated with alcohol consumption and myocardial infarction." (PMID 34384432, 2021). "During a heart attack, neutrophils rapidly activate and differentiate into a specific subset characterized by high levels of MMP9, a tissue‐damaging enzyme, via the SPI1/CST7 pathway." (PMID 40151877, 2025).
hepatocellular carcinoma (2 papers, 2023 to 2024). A malignant tumor that arises from hepatocytes. "The activation of memory CD4 T-cell-associated genes CST7, CD5L, hsa-miR-23b-3p, and hsa-miR-23a-3p may correlate with the prognosis of hepatocellular carcinoma." (PMID 37139238, 2023).
melanoma (2 papers, 2020 to 2023). A malignant, usually aggressive tumor composed of atypical, neoplastic melanocytes. "Among them, many of these genes have been confirmed to be closely related to melanoma, such as the reduction of MITF level promoting melanoma invasion, tumor regression being abrogated by silencing CCL5 and CST7 being significantly up-regulated in melanoma patients who respond to ICB treatment." (PMID 38008419, 2023).
tauopathy (2 papers, 2024 to 2026). Neurodegenerative disorders involving deposition of abnormal tau protein isoforms (tau proteins) in neurons and glial cells in the brain. "Cst7, a lysosomal protease inhibitor, has been shown to modulate microglial inflammatory responses in tauopathy models, while Clec7a (Dectin‐1) mediates amyloid‐beta phagocytosis." (PMID 41508419, 2026). "In contrast to the amyloid-β models, the Cst7+ population was very limited in the P301S tauopathy mouse model, and we could barely detect Ctnna3+ microglia in this model." (PMID 39592224, 2024).
Anxiety (1 paper, 2024). Intense feelings of nervousness, tension, or panic often arise in response to interpersonal stresses. "The results of this study indicated that TSA administration relieved the behaviors of depression and anxiety in APP/PS1 mice, and decreased CST7 levels in the hippocampus of APP/PS1 mice and LPS-induced BV2 cells." (PMID 38572429, 2024). "Thus, we hypothesized that TSA might alleviate anxiety- and depression-like behaviors in APP/PS1 mice by inhibiting CST7-related microglial inflammatory response." (PMID 38572429, 2024).
asthma (1 paper, 2021). "Among these genes, most have been associated with immune response or asthma, such as HNMT, SYNJ2, or CST7." (PMID 34834492, 2021). "Lastly, CST7 is a gene that participates in eosinophil survival in the lungs, which potentially impacts asthma pathogenesis." (PMID 34834492, 2021).
bladder cancers (1 paper, 2025). "Interestingly, CST7 expression was associated with most infiltrating lymphocytes in bladder cancers." (PMID 40747123, 2025). "CST6, CSTA, and CSTB were upregulated, while CST3 and CST7 were downregulated in bladder cancer tissues." (PMID 40747123, 2025). "In bladder cancer tissues, CST1, CST2, CST6, CSTA, and CSTB were significantly upregulated, while CST3 and CST7 were downregulated compared to benign tissues." (PMID 40747123, 2025).
brain inflammation (1 paper, 2024). "Another study pointed out that the OA2 microglial cell subset promotes age-related brain inflammation by expressing some unique inflammatory signals (such as Lgals3 Cst7 Ccl4 Ccl3 Il1b)." (PMID 39440247, 2024).
cognitive deficits (1 paper, 2024). "Cystatin F dimers especially rapidly exacerbated the deposition of Aβ in the brain and cognitive deficits in 5XFAD transgenic mice, suggesting that this protein is a promising target in peripheral blood." (PMID 38730470, 2024). "Monocyte-derived cystatin F exacerbate Aβ deposition in the brain and cognitive impairment in APP/PS1 mice." (PMID 38730470, 2024). "Monocyte-derived cystatin F increased Aβ deposition and exacerbated cognitive deficits in APP/PS1 mice." (PMID 38730470, 2024). "We demonstrated that cystatin F expression was specifically elevated in the monocytes of sporadic AD patients and that in vivo, human cystatin F aggravated Aβ deposition in the brain and cognitive impairment in APP/PS1 mice." (PMID 38730470, 2024).
Creutzfeldt-Jakob disease (1 paper, 2017). "Collectively, these analyses indicate the lack of a significant increase of cystatin F levels in CSF samples of Creutzfeldt-Jakob disease cases compared to clinically relevant controls." (PMID 28178353, 2017).
cyst (1 paper, 2020). A sac-like closed membranous structure that may be empty or contain fluid or amorphous material. "Due to their cyst wall localizations, TgME49_258870, TgME49_204340, and TgME49_310790 were renamed CST7, CST8, and CST9, respectively." (PMID 32019789, 2020). "Similar to what has been seen with CST1 and MAG1, we found that CST7, -8, -9, and -10 also display some degree of tachyzoite parasitophorous vacuole matrix localization but localize to the cyst wall and matrix in the bradyzoite stage." (PMID 32019789, 2020). "For example, proteins CST3, CST5, CST6, CST7, GRA3, and GRA14 were detected in the cyst wall proteome but not within the interactome." (PMID 32019789, 2020).
demyelinating disease (1 paper, 2024). A broad group of disorders that affect the myelin sheaths that cover the neurons. "In this study, we set out to determine if cystatin F is involved in this process of modulating white matter damage and repair in a viral model of demyelinating disease and employed a novel Cst7 knockout (Cst7-/-) mouse to assess the response to JHMV infection." (PMID 38879499, 2024). "Our finding that microglia were the dominant cellular source of cystatin F transcripts within the brains and spinal cords of JHMV-infected mice is consistent with reported expression patterns of cystatin F within the context of pre-clinical animal models of demyelinating diseases." (PMID 38879499, 2024).
depression (1 paper, 2024). "We then compiled data from published datasets to show that Cystatin-F (CST7) is the common gene between disease-associated microglia (DAM) genes and depression-associated (DA) genes." (PMID 38572429, 2024).
encephalitis (1 paper, 2017). An acute inflammatory process affecting the brain parenchyma. "Conversely, cystatin F was detectable, mainly in infiltrating cells, in cases of encephalitis, as well as in other tissues known to express cystatin F such as bone marrow." (PMID 28178353, 2017).
Kawasaki disease (1 paper, 2021). A rare inflammatory disease characterized by an acute febrile, systemic, self-limiting, medium-vessel vasculitis primarily affecting children. "Finally, in the case of sterile inflammation, CST7 expression was increased in both systemic onset idiopathic juvenile arthritis (SOJIA) and Kawasaki disease (effect size = 0.6 and 1.02 respectively)." (PMID 33868254, 2021).
leiomyoma (1 paper, 2007). A well-circumscribed benign smooth muscle neoplasm characterized by the presence of spindle cells with cigar-shaped nuclei, interlacing fascicles, and a whorled pattern. "A balance between cell growth and apoptosis is critical in progression of tissue fibrosis and the expression of several genes functionally related to these categories, including Bcl-XL, Bad, Bax, p27Kip1, p57Kip2, Gas1, Gas7, CST6, CST7, caspases, etc., were identified in leiomyomas and myometrium." (PMID 17716379, 2007).
lung adenocarcinoma (1 paper, 2025). A carcinoma that arises from the lung and is characterized by the presence of malignant glandular epithelial cells. "Moreover, the initial MR analysis revealed heterogeneity for the associations between Cystatin D and lung adenocarcinoma, Cystatin M (prot‐a‐703) and squamous cell lung carcinoma, and Cystatin F and NSCLC." (PMID 40641363, 2025). "Significant heterogeneity was noted in the relationships between Cystatin D and lung adenocarcinoma (Q = 33.837, p < 0.001), Cystatin M (prot‐a‐703), and squamous cell lung carcinoma (Q = 25.73, p = 0.002), and Cystatin F and NSCLC (Q = 22.881, p = 0.029)." (PMID 40641363, 2025).
pancreatic cancer (1 paper, 2023). "Interestingly, genes associated with pancreatic cancer such as MALAT1 (noncoding RNA), CTRB2 (serine protease), CST7 (cysteine peptidase inhibitor), and BTG1 (anti-proliferation factor) were picked in multiple topics." (PMID 36968070, 2023).
scrapie (1 paper, 2017). A fatal disease of the nervous system in sheep and goats, characterized by pruritus, debility, and locomotor incoordination. "We also studied cystatin F levels in brains of C57BL/6 mice at different time points after intracerebral challenge with the 22L inoculum, another strain of rodent-adapted scrapie prions." (PMID 28178353, 2017).
squamous cell lung carcinoma (1 paper, 2025). A carcinoma arising from squamous bronchial epithelial cells. "No causal relationships were found for genetically predicted Cystatin B (ebi‐a‐GCST90085722), Cystatin B (prot‐b‐3), Cystatin D, Cystatin F, Cystatin M (prot‐a‐703), or Cystatin M (prot‐a‐704) with squamous cell lung carcinoma (all p > 0.05)." (PMID 40641363, 2025).
tuberculosis (1 paper, 2021). A chronic, recurrent infection caused by the bacterium Mycobacterium tuberculosis. "In tuberculosis (TB), CST7 was significantly upregulated (effect size = 0.84)." (PMID 33868254, 2021).
uveitis (1 paper, 2025). An inflammatory process affecting a part of or the entire uvea. "However, there has not been a well-established association between uveitis and CST7 or GNLY." (PMID 40270958, 2025). "Importantly, only three IRGs (CR1, CST7, and GNLY, all regulated by IFN types I and II) were differentially expressed in both uveitis groups, differing on regulation among groups." (PMID 40270958, 2025).
viral infection (1 paper, 2024). "How cystatin F impacts neurologic disease severity following viral infection of the central nervous system (CNS) has not been well characterized and was the focus of this study." (PMID 38879499, 2024).